VTI1A (vesicle transport through interaction with t-SNAREs 1A)
Description:
V-SNARE that mediates vesicle transport pathways through interactions with t-SNAREs on the target membrane. These interactions are proposed to mediate aspects of the specificity of vesicle trafficking and to promote fusion of the lipid bilayers. Involved in vesicular transport from the late endosomes to the trans-Golgi network. Along with VAMP7, involved in an non-conventional RAB1-dependent traffic route to the cell surface used by KCNIP1 and KCND2. May be involved in increased cytokine secretion associated with cellular senescence.
Synonyms: MVti1; Vti1-rp2; MMDS3; VTI1RP2
Tractability: Antibody: UniProt predicts a signal peptide or a membrane-spanning region. PROTAC: ubiquitination databases record sites on it; its protein half-life has been measured.
Gene: Protein-coding gene on chromosome 10 (112,446,998 to 112,818,744, forward strand). Ensembl gene ENSG00000151532.
Subcellular location: Cytoplasmic vesicle; Golgi apparatus membrane
Subcellular location (Human Protein Atlas): Golgi apparatus; Vesicles
Pathways (Reactome):
Vesicle-mediated transport: Intra-Golgi traffic; Retrograde transport at the Trans-Golgi-Network
Gene Ontology:
Molecular function: protein binding; SNAP receptor activity; SNARE binding
Biological process: autophagy; endocytic recycling; retrograde transport, endosome to Golgi; voluntary musculoskeletal movement; endoplasmic reticulum to Golgi vesicle-mediated transport; Golgi to vacuole transport; intra-Golgi vesicle-mediated transport; macroautophagy; vesicle fusion with Golgi apparatus; endosomal transport; intercellular transport; intracellular protein transport; membrane fusion; vesicle-mediated transport
Cellular component: autophagosome; Golgi apparatus; clathrin-coated vesicle; endoplasmic reticulum membrane; endosome; ER to Golgi transport vesicle membrane; Golgi membrane; late endosome membrane; neuron projection terminus; neuronal cell body; perinuclear region of cytoplasm; SNARE complex; synaptic vesicle; trans-Golgi network membrane; bounding membrane of organelle; cytoplasm; cytoplasmic vesicle; cytosol; endomembrane system; membrane
Genetic constraint (gnomAD): Loss-of-function variants: 22 observed, 36.36 expected, observed/expected ratio (o/e) 0.61, 90% interval 0.43 to 0.86. The upper end of that interval is the gene's LOEUF score, 0.86, which puts it in group 3 of 6, group 1 being the genes least tolerant of losing a copy. Missense variants: 268 observed, 288.64 expected, observed/expected ratio (o/e) 0.93, 90% interval 0.84 to 1.03. Synonymous variants: 87 observed, 103.15 expected, observed/expected ratio (o/e) 0.84, 90% interval 0.71 to 1.01.
Homologues: Orthologues: chimpanzee VTI1A (100% identical), guinea pig VTI1A (98% identical), pig VTI1A (97% identical), rat Vti1a (96% identical), mouse Vti1a (95% identical), rabbit VTI1A (88% identical), macaque VTI1A (87% identical), dog VTI1A (87% identical), tropical clawed frog vti1a (79% identical), zebrafish vti1a (79% identical), Caenorhabditis elegans vti-1 (43% identical), Drosophila melanogaster Vti1a (40% identical). Paralogues in human: VTI1B (32% identical), GOSR2 (19% identical).
Diseases named in the same sentence as VTI1A in open-access papers:
VTI1A is named in the same sentence as 30 diseases in open-access papers, as found by Europe PMC text mining. Sharing a sentence is not in itself a finding about the gene and the disease. The quoted sentences say what the papers report.
glioma (6 papers, 2015 to 2025). A benign or malignant brain and spinal cord tumor that arises from glial cells (astrocytes, oligodendrocytes, ependymal cells). "On the other hand, although CFAP46 role in breast cancer is not yet clear, gene fusion involving various other genes such as VTI1A (reported to cause the initiation of glioma and other cancers) has been reported to play a role in breast cancer." (PMID 39723380, 2024). "A previous study identified VTI1A as one of the susceptibility genes for glioma in European populations." (PMID 35711736, 2022). "Furthermore, Vti1a forms transcriptional complexes with adjacent genes, and Vti1a variants play critical roles in glioma." (PMID 35711736, 2022). "In addition, the results of a meta-analysis of four genome-wide association studies on glioma revealed that the VTI1A SNP variant rs11196067 was a susceptibility gene in glioma." (PMID 35711736, 2022). "Studies have shown that Vti1a plays a substantial role in some neurological disorders; Vti1a gene variants and fusion transcripts with adjacent genes are involved in gliomas; Vti1a plays a key role hepatic encephalopathy by regulating spontaneous neurotransmitter transmission." (PMID 35711736, 2022). "Moreover, VTI1A was validated to have susceptibility loci for late-onset AD, even in glioma, based on a genome-wide association study." (PMID 32154224, 2020). "Interestingly, in 473 Chinese glioma, the VTI1A single nucleotide polymorphism (SNP) variant rs11196067 was significantly associated with its risk, suggesting that VTI1A variants might increase the susceptibility of individuals to glioma." (PMID 35711736, 2022). "A VTI1A variant is associated with the risk of glioma, and the fusion product of the VTI1A gene and the adjacent TCF7L2 gene is involved in glioma development." (PMID 35711736, 2022). "Collectively POLR3B, ETFA, VTI1A, ZBTB16 and PHLDA1 are altered in 8% (22/286) of LGG as compared with 3% (8/273) of GBM (P=0.014) providing support for these genes having a role in glioma tumorigenesis." (PMID 26424050, 2015).
colorectal cancer (3 papers, 2018 to 2023). A primary or metastatic malignant neoplasm that affects the colon or rectum. "Sequencing of primary colorectal tumors has identified a gene fusion in approximately 3% of colorectal cancer patients of the VTI1A and TCF7L2 genes, encoding a VTI1A-TCF4 fusion protein containing a truncated TCF4." (PMID 29975781, 2018). "Studies have shown that fusion of the VTI1A and TCF7L2 genes, encoding a VTI1A-TCF4 fusion protein containing truncated TCF4, regulates the Wnt signaling pathway and participates in colorectal cancer development." (PMID 35711736, 2022). "COSMIC fusion VTI1A::TCF7L2, originally identified as an oncogenic fusion in colorectal cancer, was most abundant in stomach, colon, and esophageal carcinoma samples but was also detected in seven individual GTEx normal samples (brain, whole blood, tibial nerve, tibial artery, prostate, and breast)." (PMID 37323575, 2023).
colon cancer (2 papers, 2014 to 2023). "With regards to structural events in colon cancer, gene fusions of TCF7L2 with VTI1A have previously been observed in 3% of the colon cancers." (PMID 24943349, 2014).
lung carcinoma (2 papers, 2016 to 2019). "The corresponding SNP rs7086803 of VTI1A (vesicle transport through interaction with t-SNAREs 1A) was only identified in female non-smoking Asians as the strongest association signal of lung cancer." (PMID 27323854, 2016). "We identified methylation changes in three genes, VTI1A, STK32A and GATA3 that were rarely reported in relation to lung cancer among Caucasians previously." (PMID 27323854, 2016).
amyotrophic lateral sclerosis (1 paper, 2022). Amyotrophic lateral sclerosis (ALS) is a neurodegenerative disease characterized by progressive muscular paralysis reflecting degeneration of motor neurons in the primary motor cortex, corticospinal tracts, brainstem and spinal cord. "Another study on the expression of glycogen synthase kinase 3beta in the spinal cord of amyotrophic lateral sclerosis (ALS) reported decreased TGN GSK3beta expression in motor neurons, as well as Vti1a." (PMID 35711736, 2022).
atherosclerosis (1 paper, 2024). A disease characterized by the build-up of fatty material and calcium deposition in the arterial wall resulting in partial or complete occlusion of the arterial lumen. "The five key genes related to three pathways included the SNARE interactions in the vesicular transport pathway (SNAP23, VTI1A), the insulin signaling pathway (IRS2, PRKAR1A), and lipid and atherosclerosis (CASP1)." (PMID 38674428, 2024).
depression (1 paper, 2024). "Accordingly, SNARE interactions in the vesicular transport pathway that involve SNAP23 and VTI1A is proven to be a vital signaling pathway in the patients with PCOS and depression." (PMID 38674428, 2024). "There were five overlapping hub genes in the two datasets including CASP1, IRS2, PRKAR1A, SNAP23, and VTI1A, which were identified as the key genes in the comorbidity of PCOS and depression." (PMID 38674428, 2024). "Thus, for the same reason as SNAP23, VTI1A is evidenced to be a key gene in the comorbidity of PCOS and depression." (PMID 38674428, 2024).
lentivirus infection (1 paper, 2017). Virus diseases caused by the Lentivirus genus. "In order to assess the impact of these vesicular SNAREs on synaptic efficacy, we cultured rat hippocampal neurons and used vti1a and VAMP7 short hairpin RNA (shRNA) expression via lentivirus infection to reduce vti1a and VAMP7 protein levels." (PMID 28186166, 2017).
liver cancer (1 paper, 2023). An epithelial or non-epithelial malignant neoplasm that arises from the liver. "In the liver cancer, Marco (red), Vti1a (green), F13a1 (blue) are largely expressed in Monocyte cells when contacting Hepatocyte I (Monocyte+Hepatocyte I), Hepatocyte II (Monocyte+Hepatocyte II), and Tumor III (Monocyte+Tumor III), respectively." (PMID 37815040, 2023).
neuroblastoma (1 paper, 2022). Neuroblastoma (NB) is the most common solid, extracranial childhood tumor. "Vti1a and vti1b are expressed in every tissue and cell type analyzed including chromaffine cells and several neuroblastoma cell lines." (PMID 36419086, 2022).
tumor (8 papers, 2014 to 2025). "We also detected COSMIC fusion VTI1A::TCF7L2 across multiple tumor and normal tissue types (consistent with Nome et al68)." (PMID 37323575, 2023). "Two nodes of module 1,” U2AF1” and “BCL1”, are oncogenes and “NAB2” is a tumor suppressor and “VTI1A” is a fusion gene." (PMID 35525925, 2022). "Based on these results, we suggest that the fusion transcripts produced between TCF7L2 and either VTI1A or RP11-57H14.3 are expressed at low levels in tumor samples, and some normal samples." (PMID 24608966, 2014). "In short, abnormal Vti1a may affect Wnt-interacting receptor signaling or promote tumor cell migration in an as yet undetermined manner, but the exact mechanism is unclear." (PMID 35711736, 2022). "For example, one study found that the Vti1a gene transcript could be detected in tumor tissue and serum of GBM." (PMID 35711736, 2022). "Specially, FGFR2 rearrangements (FGFR2/VTI1A and FGFR2/TACC2) were recurrently detected in 3.1% (2/64) PC GC tumor samples." (PMID 34551773, 2021).
cancer (7 papers, 2013 to 2025). A tumor composed of atypical neoplastic, often pleomorphic cells that invade other tissues. "Furthermore, VTI1A variants are associated with cancer risk." (PMID 35711736, 2022). "However, studies have reported that the fusion product between the human VTI1A gene and adjacent genes plays an important role in the occurrence of cancer." (PMID 35711736, 2022).
neurological diseases (2 papers, 2021 to 2022). "Similar to the DPP6 gene, Tang’s study found that VTI1A is mainly involved in neuronal development and neurotransmission, and mutations are likely to lead to neurological dysfunction and neurological diseases." (PMID 34684344, 2021). "This review summarizes Vti1a functions in neurons and highlights the role of Vti1a in the several nervous system disorders." (PMID 35711736, 2022). "Therefore, Vti1a is highly relevant in neurological diseases and presents substantial research potential." (PMID 35711736, 2022).
infection (1 paper, 2023). The state of being infected such as from the introduction of a foreign agent such as serum, vaccine, antigenic substance or organism. "Interestingly, the strongest decrease in infection was detected for the knockouts of three vesicular trafficking proteins (VTI1A, STX12 and STX16), highlighting the important role of vesicular trafficking for SARS-CoV-2 infection and replication." (PMID 37632105, 2023).
VTI1A also shares sentences with these, for which no sentence is quoted: breast carcinoma (2 papers); allergic asthma (1); asthma (1); astrocytoma (1); breast tumors (1); childhood asthma (1); colorectal adenocarcinoma (1); colorectal tumors (1); eosinophilia (1); esophageal carcinoma (1); glioblastoma (1); hematologic cancer (1); lung adenocarcinoma (1); Obesity (1); ovarian carcinoma (1); uterine cancer (1).